SDC1 (syndecan 1)
Diseases named in the same sentence as SDC1 in open-access papers (continued):
Sharing a sentence is not in itself a finding about the gene and the disease.
breast carcinoma (continued). "Indeed, it has been observed that in MDA-MB-231 human breast cancer cells SDC1 physically interacts with FAK." (PMID 25140302, 2014). "Similarly, the distinct roles of transmembrane and shed forms of Syndecan-1 (Sdc1) in breast cancer progression were revealed." (PMID 24809485, 2014). "Moreover, a study conducted in postmenopausal women with breast cancer or dense-mammographic breast tissue demonstrated that the distribution of SDC1 changes from the epithelium to the stroma." (PMID 25140302, 2014). "It has been proposed that CDCP1 interacts with SDC1 in a human breast cancer cell line, MDA-468." (PMID 25275584, 2014). "Indeed in breast cancer, SDC1 is suggested to be a poor prognostic factor for breast cancer since its upregulation at both the mRNA and protein levels has been associated with higher histological tumor grade, as well as increased mitotic index and tumor size." (PMID 25140302, 2014). "According to our findings, Syndecan-1 silencing in triple-negative MDA-MB-231 breast cancer cells inhibited proinflammatory signaling via downregulation of relevant receptors and ligands (IL-6/IL6-R/CCL20), which was linked to reduced constitutive activation of NFkB and STAT3." (PMID 24392029, 2013). "As such, the upregulation of two cell-surface PGs, glypican-1 (GPC1) and syndecan-1 (SDC1), and of the extracellular sulfatase Sulf-2, have been described in malignant breast cancer tissues whilst the downregulation of some genes including SULF1 and HS3ST2 has also been reported." (PMID 23327652, 2013). "Furthermore, experimental and clinical data have shown that the expression of syndecan-1 by the stromal fibroblasts promotes breast carcinoma growth in vivo and stimulates tumour angiogenesis." (PMID 23844358, 2013). "Based on these findings, we hypothesize that Syndecan-1 may regulate human breast cancer stem cell function." (PMID 24392029, 2013). "In line with our data in human breast cancer cell lines, these findings highlight that Syndecan-1 expression might potentiate Wnt signaling via regulation of LRP-6 coreceptor expression even in the absence of Wnt ligand overexpression." (PMID 24392029, 2013). "High expression of Syndecan-1 in breast cancer is associated with negative progostic parameters and reduced breast cancer-specific overall survival." (PMID 24392029, 2013). "Out of 13 HSPGs, only SDC1 has been shown as overexpressed in breast cancer." (PMID 24373193, 2013). "Here, we decipher the functional impact of Syndecan-1 knockdown using RNA interference on the breast cancer stem cell phenotype of human triple-negative MDA-MB-231 and hormone receptor-positive MCF-7 cells in vitro employing an analytical flow cytometric approach." (PMID 24392029, 2013). "SDC1-null mice showed inhibition of mammary tumor development and WNT-dependent tumor initiation." (PMID 24373193, 2013). "In addition, a study using breast cancer cells observed that membrane-bound syndecan-1 increased cell proliferation, whereas soluble syndecan-1 increased cell invasion." (PMID 22905270, 2012). "Moreover, Sdc-1 expression is suppressed during the steroid-induced conversion of S115 mouse mammary tumor cells from an epithelioid to a fibroblastoid morphology." (PMID 22912899, 2012). "The expression of syndecan-1 in breast cancer is described as a poor prognostic factor." (PMID 22214534, 2011). "In addition, recent studies of human breast cancer have shown that n-3 PUFAs up-regulate syndecan 1 (SDC-1), which has been shown to play a role in cell adhesion, inhibit matrix metalloproteinases and decrease invasion of tumour cells." (PMID 21569413, 2011). "Syndecan-1 appears particularly interesting for breast carcinoma radioimmunotherapy (RIT)." (PMID 22214534, 2011). "A549 cell lines are cancerous in origin, and thus, changes associated with the transformed phenotype may have altered the functions of syndecan-1 and the pathways controlling cell movement, such as that seen with breast cancer cells." (PMID 19668337, 2009).
breast carcinoma (continued). "Furthermore, experimental and clinical data have shown that the expression of syndecan-1 in the stroma promotes breast carcinoma growth in vivo and stimulates tumour angiogenesis." (PMID 18542065, 2008). "In breast carcinomas, three studies have been devoted to the expression of syndecan-1." (PMID 18542065, 2008). "Moreover, we characterized the coexpression of Sdc1, E-cad and c-met in three differently aggressive human breast cancer cell lines by RT-PCR and by confocal immunofluorescence microscopy." (PMID 17244359, 2007). "Thus, this study primarily aimed to investigate whether pre-diagnostic serum levels of SDC1 and SDC4 were associated with breast cancer risk in a prospective population-based cohort." (PMID 40694191, 2025). "Although other PGs may also be involved in CHPF-regulated breast cancer malignancy, this study provides the first evidence that a CS synthase participates in the regulation of macropinocytosis in cancer cells by supporting SDC1 expression on cancer cells." (PMID 38770553, 2024). "Importantly, our results showed that breast cancer patients with highly expressed SDC1 had lower overall survival than those with low SDC1 expression, suggesting that SDC1 may be a target for harmful cellular interactions." (PMID 37021816, 2023). "Studies on MDA-MB-231 breast cancer cells found an association between Sdc-1 and Rho-GTPase in the regulation of cell motility, and in contrast to HeLa cells, MDA-MB-231 cell motility was increased via the Rho signaling pathway upon pathway upon Sdc-1 depletion." (PMID 35155241, 2022). "Moreover, membrane-bound and Sdc-1-WT promoted invasion of breast cancer cells in vitro." (PMID 35155241, 2022). "Deletion of the C2 region of Sdc1 or the last 28 amino acids in the β4 integrin tail (Δ1728-1752), or mutation of R1733 within this sequence, abolishes the interaction, prevents tyrosine phosphorylation of the integrin and blocks epithelial cell migration on LN332 and breast carcinoma cell survival." (PMID 34778093, 2021). "Moreover, Sdc-1 of stromal fibroblasts induced breast carcinoma growth and angiogenesis in vivo." (PMID 34066023, 2021). "Moreover, the triple-negative aggressively invasive MDA-MB-231 breast carcinoma line could also be a source of TGF-β for paracrine activation of syndecan-1 expression." (PMID 33921767, 2021). "We further analyzed the relationship between SDC1 expression and clinicopathologic parameters including prognostic significance, and explored the biological function and molecular mechanism of SDC1 in breast cancer patients by pooling all currently available data." (PMID 29340066, 2017). "Additionally, SDC1 is positively associated with PLAU and might act as a potential prognostic indicator for breast cancer." (PMID 29340066, 2017). "Furthermore, miR-10b could target the syndecan-1 gene and promoted breast cancer cell motility and invasiveness through a Rho-GTPase-dependent and E-cadherin-dependent mechanism." (PMID 28691018, 2017). "However, increased SDC1 expression has been reported in breast cancer and pancreatic cancer." (PMID 24373193, 2013). "Similarly, Sdc1 regulates αvβ3 integrin activation and signalling in breast cancer cell lines." (PMID 17244359, 2007). "Moreover, we showed that serum-activated fibroblasts exhibit many molecular similarities to the fibroblasts that naturally infiltrate human breast cancer, including expression of syndecan-1, α-smooth muscle actin, and genes related to myofibroblast differentiation and activation by TGF-β." (PMID 15987422, 2005). "SDC1 relies on the IL-6/STAT3, Notch and EGFR pathways to induce stem cell formation in breast cancer, Ibrahim et.al." (PMID 41364407, 2025). "We discovered that the expression of SDC1 in tumor cells was positively correlated with overall survival (OS) and event-free survival (EFS) in breast cancer patients, particularly among those with luminal subtypes." (PMID 41364407, 2025).
breast carcinoma (continued). "In breast cancer, tumor stiffness induces an increase in the extracellular pressure which promotes HSPG formation and its protein syndecan-1 can align collagen into stiffer and parallel collagen fibers." (PMID 40643556, 2025). "Based on the TCGA-BRCA dataset, we found that LOXL1, SDC1 and PXDNL were highly expressed in breast cancer while the expressions levels of FBLN1, FBLN5 and ADAMTS8 were lower than those in normal breast samples." (PMID 37056938, 2023). "In this study, BM genes with differential expression and prognostic correlation in breast cancer were selected as promising prognostic biomarkers for breast cancer, including FBLN1, FBLN5, ADAMTS8, LOXL1, SDC1 and PXDNL." (PMID 37056938, 2023). "Since adipose tissue plays a pivotal role in breast cancer progression, the interplay between SDC1 and PPAR-gamma needs further investigation in order to establish new potential therapeutic strategies for breast cancer." (PMID 36980680, 2023). "To further explore the mechanism of SDC1 in breast cancer, especially in TNBC, we conducted cell experiments to evaluate the effects of SDC1 on breast cancer cell proliferation and migration." (PMID 37069585, 2023). "Taken together, these findings highlight the prognostic significance of SDC1 and SDC4 in breast cancer." (PMID 36980680, 2023). "In breast cancer tissue samples, MMP1, SDC1, CD24, and SPP1 showed higher protein expression compared with that in tumor-adjacent tissues, and their expression was positively correlation with tumor subtype and grade." (PMID 35037689, 2022). "In the luminal B subtype, SDC1 and SPP1 expression was significantly correlated with prognosis of breast cancer patients." (PMID 35037689, 2022). "Higher MMP1, SDC1, SPP1, and CD24 expression was correlated with worse overall survival (OS) and relapse-free survival (RFS) in breast cancer patients." (PMID 35037689, 2022). "We developed a novel GRG signature of six GRGs, including CACNA1H, CHPF, IRS2, NT5E, SDC1 and ATP6AP1, to predict survival and guide individual therapy in breast cancer." (PMID 36277284, 2022). "Our results indicated that MMP1, CD24, SDC1, and SPP1 are potential novel prognostic biomarkers and candidate immunotherapy targets for breast cancer." (PMID 35037689, 2022). "The percentages of high protein expression of CD24, SDC1, and SPP1 were 28.6, 34.2, and 19.2% in breast cancer tissue, compared with 1.5, 1.5, and 1.1% in pan-cancer tissue, respectively (P=0.00, P=0.00, and P=0.00)." (PMID 35037689, 2022). "In our study, CD24 protein expression was positively correlated with tumor grade, subtype and SDC1 expression, with higher expression of CD24 in breast cancer tissues compared with tumor-adjacent tissues." (PMID 35037689, 2022). "Overexpression ofCD24, MMP1, SDC1, and SPP1 indicated the poor prognosis in breast carcinoma patients analyzed by Kaplan–Meier (KM) Plotter." (PMID 35037689, 2022). "The expression of CD24, MMP1, SDC1, and SPP1 was much higher in breast carcinoma tissue than in Para cancerous tissues analyzed by Gene Expression Profiling Interactive Analysis (GEPIA) and ONCOMINE." (PMID 35037689, 2022). "In another study, the frequency of the CD44+/CD24- population—marking breast cancer stem cells (CSCs)—was diminished, and the expression and activation of the pro-inflammatory IL-6/STAT3 pathway reduced after Sdc-1 siRNA knockdown." (PMID 34070901, 2021). "PTK7 expression in breast cancer was significantly positively correlated with COL1A1, FN1, WNT5B, MMP11, MMP14 and SDC1 in breast cancer." (PMID 34367983, 2021). "To assess the prognostic value of the Sdc-1-dependent factors, we correlated their expression with the relapse-free survival (RFS) for 3951 breast cancer patients using the online tool Kaplan–Meier Plotter." (PMID 34066023, 2021). "Knockdown of SDC1 promoted EMT, while overexpression of SDC1 induced epithelial characteristics in mammary tumor cells and oral cancer cells." (PMID 34208075, 2021).
breast carcinoma (continued). "Soluble SDC1 promotes the growth of myeloma tumors in vivo, while shed SDC2 enhances colon, lung, and breast cancer progression." (PMID 32916872, 2020). "Syndecan-1 was shown to bind OPG via its heparan sulfate proteoglycan side chains and thereby influences bone resorption during breast cancer and multiple myeloma." (PMID 33239699, 2020). "The ectodomain and HS chains of SDC1, through αvβ3 integrin, induce ECM fiber alignment that promotes the directional migration and invasion of breast carcinoma cells." (PMID 32916872, 2020). "In addition, the expression of syndecan-1, which has heparan sulfate chains and is able to promote cancer invasiveness, could be induced by ER suppression using selective ER down-regulators in breast cancer cells." (PMID 33324567, 2020). "Synstatin, a short peptide mimicking the SDC1 ectodomain responsible for αvβ3 or αvβ5 integrin/IGF1 complex formation and receptor activation, has been proved to be effective in mammary tumors and hepatocellular carcinoma." (PMID 32916872, 2020). "We have shown that in breast cancer cells specifically IBC, silencing of Sdc-1 drives downregulation of IL-6 and its signaling pathway components." (PMID 31145753, 2019). "Breast cancer cells are also shown to overexpress HSPGs, such as Glypican 1 (GPC1) and Syndecan 1 (SDC1), which enhance the proliferative response after treatment with various growth factors due to prolonged signaling." (PMID 30197623, 2018). "Given the role of stromal Sdc1 in ECM fiber assembly in vitro and in vivo, we measured the amount of collagen in the 4T1 mammary tumors by SHG imaging and collagen alignment by computer-assisted analysis of the SHG images." (PMID 29976229, 2018). "By performing data mining in bc-GenExMiner, we pooled previous available annotated genomic data to analysis the relationship between SDC1 expression and prognosis metastatic relapse-free survival (MRFS) in breast cancer." (PMID 29340066, 2017). "Conversely, in breast cancer patients with higher epidermal growth factor receptor 2 (HER2), the mRNA levels of SDC1 was significantly increased compared with HER2-negative groups." (PMID 29340066, 2017). "A strong syndecan-1 and MUC-1 expression was also documented by immunohistochemistry on primary breast cancer tissues, performed in four patients." (PMID 28399903, 2017). "We have previously shown that Syndecan-1 modulates the expression of IL-6, IL-6R in different experimental models of inflammation and in MDA-MB-231 breast cancer cells." (PMID 28270211, 2017). "Following data mining in multiple big databases confirmed a positive correlation between SDC1 mRNA expression and PLAU mRNA expression in breast cancer tissues." (PMID 29340066, 2017). "Taken together, these results indicated that IGF-IR regulates mainly syndecan-4, and to a lesser extent syndecan-1, expression and localization in ERα-positive MCF-7 breast cancer cells." (PMID 28079144, 2017). "Kaplan-Meir analysis revealed that high SDC1 mRNA was correlated with a lower overall survival (OS), relapse-free survival (RFS), distance metastasis free survival (DMFS) in breast cancer." (PMID 29340066, 2017). "Syndecan-1 facilitates the FGF2-FGFR1 complex formation in different tumor types, comprising lymphomas, breast cancer, and prostate cancer." (PMID 26420915, 2015). "For instance, in breast cancer, microRNA-10b (miR-10b) promotes invasion and metastasis of tumor cells through regulation of HOXD10, E-cadherin, and syndecan-1." (PMID 26311318, 2015). "To date, several genes and their products have been introduced to predict the prognosis of breast cancer patients, such as transmembrane protease serine 4 (TMPRSS4), c-Kit, and syndecan-1 (SDC1)." (PMID 24373193, 2013). "Fibroblasts derived from breast carcinoma tissue produce MT1-MMP, which leads to syndecan-1 shedding from tumor cells, an important step in tumor invasion, while fibroblasts derived from healthy mammary tissue do not possess the same effect." (PMID 23984412, 2013).
breast carcinoma (continued). "Our previous studies strongly supported an upregulation of SDC-1 by n-3 PUFA that resulted in reduced growth and apoptosis induction in breast cancer cells in vitro." (PMID 21655218, 2011). "Moreover, in a nude mouse xenograft model, coinjection of MDA-MB-231 breast cancer cells with Sdc-1 overexpressing and mock-transfected mouse fibroblasts resulted in significantly elevated microvessel density and a larger vessel area in tumours containing Sdc1 overexpressing stroma cells." (PMID 17244359, 2007). "Finally, our immunocytochemical studies demonstrated that serum-activated fibroblasts uniformly express high levels of syndecan-1, a proteoglycan that is abundantly and specifically expressed by the stromal cells and myofibroblasts that are present in the connective tissue of human breast cancer." (PMID 15987422, 2005). "In contrast, only DHA conjugated with albumin, but not EPA, induced apoptosis in MCF-7 breast cancer cells through upregulation of the tumor suppressor syndecan-1 (SDC-1) in a peroxisome proliferator-activated receptor (PPAR) γ-dependent manner." (PMID 39863855, 2025). "Previous research has indicated that PGK1, SDC1, SDC3, NUP43, and IL13RA1 may contribute to the development and progression of breast cancer." (PMID 39590319, 2024). "Similarly, breast cancer patients with increased PXDNL (p=0.00011) and SDC1 (p<0.0001), and decreased FBLN1 (p=0.033) and ADAMTS8 (p=0.00017) expression levels tended to have shorter disease-specific survival (DSS) time." (PMID 37056938, 2023). "In general, SDC1 is upregulated in human breast cancers in comparison to normal tissue samples; therefore, it has been considered a marker of poor prognosis." (PMID 36980680, 2023). "In conclusion, we believe that SDC1 may be a potential target for blocking the interaction between COL1A1+ CAFs and tumor cells to promote immune infiltration in breast cancer." (PMID 37021816, 2023). "We found that the protein levels of CACNA1H, CHPF, SDC1 and ATP6AP1 were higher in breast cancer tissues compared with normal tissues, while the expression levels of IRS2 and NT5E were comparatively lower in breast cancer tissues, and the expression of them is consistent with mRNA level." (PMID 36277284, 2022). "Third, four hub genes that could have important key functions in tumor growth in breast cancer, MMP1, SDC1, CD24, and SPP1, were identified using GEO and TCGA public datasets as potential prognostic biomarkers." (PMID 35037689, 2022). "The injection of 4T1 breast cancer cells did not affect plasma concentration of the following biomarkers of endothelial dysfunction: SDC-1, ESM-1, sVCAM-1, sICAM-1, sE-sel, t-PA, sP-sel, sTie-2, Ang-2, and sFLT (results not shown)." (PMID 36504711, 2022). "The 10-year breast cancer-specific survival of patients with tumors not expressing stromal syndecan-1 was 83% compared with 66% for those with positive staining." (PMID 34952631, 2021). "Our study identifies Syndecan-1 and the tissue factor pathway as novel potential therapeutic targets in the aggressive triple-negative subtype of breast cancer, for which no targeted therapies are currently available." (PMID 34066023, 2021). "We have recently discovered an overexpression of heparanase and Sdc-1 in triple-negative inflammatory breast cancer, an aggressive form of breast cancer represented by the SUM-149 cell line employed in this study." (PMID 34066023, 2021). "We observed the downregulation of the Wnt pathway ligand Wnt-3A and the Wnt-dependent transcription factor TCF7L1 in Sdc-1-depleted MCF-7 cells, which is in accordance with our previous observation of a downregulation of the Wnt-coreceptor LRP6 in Sdc-1-depleted breast cancer cells." (PMID 34070901, 2021). "Altogether, these results indicate that Sdc-1 depletion has a negative impact on the CSC phenotype of both breast cancer cell lines, as we observed a reduction in CD44 expression in MDA-MB-231 cells." (PMID 34070901, 2021).